METTL14 (methyltransferase 14, N6-adenosine-methyltransferase non-catalytic subunit)
Diseases named in the same sentence as METTL14 in open-access papers (continued):
Sharing a sentence is not in itself a finding about the gene and the disease.
tumor (continued). "In summary, these data suggested that METTL14 performed a tumour‐suppressive function via targeting SLC7A11 in an m6A‐dependent manner in HCC." (PMID 34609072, 2021). "Consistent with our in vitro observations, knockdown of METTL14 resulted in significant increase of the tumor volume and tumor weight." (PMID 32111213, 2020). "Of these candidate genes, SOX4 was reported be closely with tumor progression, and was selected as a candidate target of METTL14-mediated m6A modification for further study." (PMID 32552762, 2020). "METTL14 regulates the m6A levels of key transcripts relating to EMT and angiogenesis, thus resulting in increased gene expression and subsequent tumor-associated angiogenesis and cancer progression." (PMID 32296573, 2020). "According to the results, we can conclude that METTL14 had lower expression in the tumor samples than in the normal samples." (PMID 31943856, 2020). "As core molecules of MTC, METTL3 and METTL14 often perform an opposite effect on tumor process in same cancer." (PMID 33159022, 2020). "In hepatocellular carcinoma, METTL14 antagonizes METTL3 by suppressing tumor metastasis via interaction with DGCR8." (PMID 32709063, 2020). "Methyltransferase-like 14(METTL14), a major RNA N6-adenosine methyltransferase, is involved in tumor progression via regulating RNA function." (PMID 32552762, 2020). "METTL14 was also suggested to be an inhibitor of tumor metastasis and considered as a favorable factor in HCC via mediating m6A-dependent miRNA processing." (PMID 32038982, 2020). "In CRC, METTL14 acts as a tumor-suppressor to inhibit cell growth and metastasis in vitro and in vivo." (PMID 33015074, 2020). "Comparisons between adjacent normal and tumor samples identified seven down-regulated (METTL14, WTAP, YTHDC1, YTHDC2, ALKBH5, FTO, and YTHDF2) and one up-regulated (YTHDF1) regulators." (PMID 32500031, 2020). "Next, we further estimated METTL3 and METTL14 expression in a larger cohort containing 136 paired tumor and paratumor tissues." (PMID 32175271, 2020). "Knockdown of erasers (FTO and ALKBH5) or overexpression of writers (METTL3 and METTL14) suppressed the cellular proliferation and tumor formation of cervical cancer cells both in vitro and in vivo." (PMID 31711514, 2019). "The results showed that EBNA3C co-localized with METTL14 in PTLD tumor tissues (compare panel 5G and 5H)." (PMID 31226160, 2019). "We then detected tumor propagation of Mettl14 knockout cells through in vivo tumor propagation assay." (PMID 31760940, 2019). "As a tumor suppressive factor and a marker for epithelial phenotype, E‐cadherin changes elicited by METTL14/FTO knockdown were in line with the activation/inhibition of Wnt/PI3K‐Akt pathways." (PMID 31243897, 2019). "Meanwhile, Mettl14 deleted T24 cells showed enhanced oncosphere formation capacity, enhanced invasion capacity and tumor propagation ability." (PMID 31760940, 2019). "Consist with tumor initiation, higher ratios of bladder TICs were also detected in Mettl14 knockout cells." (PMID 31760940, 2019). "Mettl14 knockout promotes the proliferation, self-renewal, metastasis and tumor initiating capacity of bladder TICs, and Mettl14 overexpression exerts an opposite role." (PMID 31760940, 2019). "Mettl14 overexpressing cells were also used for tumor-initiating assay, and impaired tumor initiation was observed." (PMID 31760940, 2019). "LcL shCr, LcL shMETTL14, LcL shEBNA3C and LcL shMETTL14 plus shEBNA3C were subcutaneously injected into NOD-SCID mice to assess the effect of knock-down METTL14 or EBNA3C on tumor growth." (PMID 31226160, 2019). "Given a dual role of METTL14 either as a tumor suppressor or an oncogene in cancer, its role in other cancers need be further elucidated." (PMID 31142332, 2019). "Then, analyzing TCGA KIRC database, we found METTL14 mRNA was decreased in tumor tissues compared to normal tissues." (PMID 31159832, 2019).
tumor (continued). "It remained unclear how upregulated METTL3 and downregulated METTL14 together participate in tumor development." (PMID 31492150, 2019). "The results demonstrated that knock-down of METTL14 or EBNA3C led to a dramatic slowing of tumor growth compared to the control group." (PMID 31226160, 2019). "METTL14 is associated with frequent recurrence and poor survival; and abnormal levels of METTL14 are related with tumor differentiation, tumor stage, tumor encapsulation, microsatellite and microvascular invasion." (PMID 31711514, 2019). "METTL14 inhibits tumor invasion and metastasis by regulating miR-126 while promoting tumor cell proliferation and migration by regulating suppressor of cytokine signaling 2 (SOCS2)." (PMID 31722709, 2019). "Specifically, METTL14 can promote pri-miR126 processing to mature miR126, a tumor suppressor in HCC metastasis, by mediating the recognition and binding of the microprocessor protein DGCR8 to pri-miRNA." (PMID 30062093, 2018). "After testing the mRNA expression of m6A-related factors between HCC and para-tumor tissue or normal tissue, METTL14 was found to be significantly lowered in HCC tissue." (PMID 29374143, 2018). "Depletion of METTL14 revealed high metastatic capacity of HCC both in vitro and in vivo while overexpression of METTL14 suppressed tumor metastasis." (PMID 29374143, 2018). "Mice grafted with the GSCs with KD of both METTL3 and METTL14 resulted in an increase in tumor progression that was even more dramatic than that seen in mice grafted with GSCs with METTL3 or METTL14 KD alone." (PMID 28297667, 2017). "This article systematically reviews the dual regulatory role of METTL14 in tumors and its molecular mechanisms, mainly organizing the relevant research in a logical sequence of "tumor suppressive effect - tumor promoting effect - controversial or context-dependent"." (PMID 41858346, 2026). "Accumulating evidence indicates that METTL14 exerts multi-level immune regulatory effects in the TME by modulating T cells, regulatory T cells (Tregs), tumor-associated macrophages (TAMs), and natural killer (NK) cells, thereby reshaping the immune landscape and regulating antitumor immunity." (PMID 41164187, 2025). "Therefore, patient stratification based on tumor type, immune cell composition, and METTL14 expression patterns, along with the development of cell-type-specific delivery systems, will be critical for safe and effective therapeutic interventions." (PMID 41164187, 2025). "Sphere-forming assays showed that METTL14-US could markedly inhibit the tumor-forming capacity compared to METTL14-UL." (PMID 40290127, 2025). "In our research, the regulatory function of mechanic-m6A on YAP1 was identified in response to the PDAC heterogeneous stiffness, in which local stiff niches enhance YAP1 levels to boost the tumor cell stem-like type via METTL14/IGF2BP3-suppressed YAP1 mRNA decay." (PMID 40822927, 2025). "In this way, EBNA3C exploits METTL14 to regulate tumour formation." (PMID 41019992, 2025). "Similar to previous results, inhibiting METTL14 expression could impair the proliferation ability and motility of tumor cells, promoting an increase in cell apoptosis; at the same time, it downregulated the expression of MAP2K7, p-ERK, and p-p38MAPK molecules." (PMID 41323393, 2025). "METTL3 and METTL14 work together as a tumor suppressor in endometrial carcinoma." (PMID 40483535, 2025). "In conclusion, research on METTL14 in tumor immunity remains in rapid evolution." (PMID 41164187, 2025). "Therefore, this review aims to systematically summarize the molecular mechanisms and biological functions of METTL14 in tumor immunity, and to further discuss its potential value and translational prospects in immunotherapy." (PMID 41164187, 2025).
tumor (continued). "Additional evidence shows that circZNF548, downregulated in NSCLC and associated with favorable prognosis, enhances CD8+ T-cell cytotoxicity via exosomal miR-7108-3p, while METTL14 reduces circZNF548 levels through m6A modification, thereby promoting tumor progression." (PMID 41164187, 2025). "As a core component of the m6A methyltransferase complex, METTL14 not only promotes tumor initiation and progression through post-transcriptional regulation of cancer cells, but also profoundly influences the differentiation, functional maintenance, and intercellular communication of immune cells." (PMID 41164187, 2025). "Systemic targeting of METTL14 could inadvertently disrupt immune homeostasis or impair anti-tumor immunity in specific contexts." (PMID 41164187, 2025). "Thus, METTL14 exhibits tumor-type-dependent roles in metastasis, underscoring that m6A machinery must be interpreted within disease context and cellular wiring." (PMID 41301491, 2025). "For instance, inhibiting METTL3 or METTL14, which increase PD-L1 expression on tumor cells, could reduce immune escape and restore T-cell activity, thus enhancing the response to immune checkpoint blockade." (PMID 39911396, 2025). "METTL14 exerts a dual impact in the occurrence and progression of various cancers, acting else as a tumor suppressor gene or as an oncogene, with its specific function depending on the type of tumor and its microenvironment." (PMID 41323393, 2025). "Despite significant progress in research, there are still many challenges in this field: the functional background of writers is dependent, and the same writer (such as METTL3, METTL14) can play completely opposite roles in different tumors or even within the same tumor." (PMID 41256854, 2025). "Overall, METTL14 ensures effective innate immune surveillance through m6A-dependent mechanisms, reinforcing its central role as a molecular hub linking epitranscriptomic modification with tumor immunity." (PMID 41164187, 2025). "METTL14‐mediated m6A modification may influence tumor cell programmed cell death by regulating the mRNA decay of negative immune regulators." (PMID 39802639, 2025). "Mettl14 is critical for hepatocyte renewal, differentiation, and tumor growth." (PMID 39911396, 2025). "Firstly, the biological effects of m6A regulators such as METTL3 and METTL14 vary significantly across different cancer types, as these enzymes may promote tumor progression in one context while acting as tumor suppressors in another." (PMID 40734692, 2025). "Furthermore, GPX2 levels elevated in tumor tissues compared with normal tissues, while METTL14 levels declined." (PMID 40533443, 2025). "Notably, existing literature and reviews have largely focused on the role of METTL14 in tumorigenesis and cancer progression, while its contribution to tumor immune regulation remains relatively underexplored." (PMID 41164187, 2025). "Inhibition of METTL14 activity or downregulation of its expression has been shown to decrease PD-L1 levels, restore T cell function, and reverse the immunosuppressive status of the tumor microenvironment." (PMID 39911396, 2025). "Epigenetic modifiers such as KMT2D, BCOR, METTL3 and METTL14 were a limiting factor for uncontrolled cell proliferation in 3D spheroids, which may reveal the mechanism of how they function as tumor suppressors in human cancer." (PMID 38853928, 2025). "Additionally, total m6A richness in the tumours was positively correlated with the expressions of METTL14 and ZFP14." (PMID 39936533, 2025). "While our in vitro models provide valuable mechanistic insights into the role of METTL14 in the regulation of immune‐ and inflammation‐related genes, they inherently lack the complexity of the tumor microenvironment (TME) and the systemic interactions that occur in vivo." (PMID 41316520, 2025).
tumor (continued). "Furthermore, we demonstrated that METTL3 and METTL14 function as tumour suppressors by facilitating the maturation of miR‐146a‐5p, which in turn inhibited the migration and invasion abilities of GBC cells both in vitro and in vivo." (PMID 40785027, 2025). "Moreover, inhibition of METTL3 or METTL14 expression also enhanced tumor growth upon transplantation of GSC cells into mouse brains." (PMID 38398118, 2024). "In contrast, METTL3 and METTL14 showed a tumor-suppressive role in glioblastoma stem cells." (PMID 38503745, 2024). "It has been reported that METTL14 acts as a tumour suppressor gene in CRC progression." (PMID 39657309, 2024). "Moreover, in vivo experiments showed METTL14 knockdown remarkably reduced tumor burden and prolonged the survival of mice." (PMID 39054337, 2024). "Finally, the relationship between METTL14 and MSTRG.292666.16, and the effects of METTL14 on tumor growth in vivo were studied." (PMID 38326804, 2024). "Although the loss of METTL14 promoted tumor proliferation in vivo, no impacts on the proliferation of CRC cells in vitro were observed." (PMID 39136000, 2024). "In vivo experiments showed that the volume of the tumor increased over time, but METTL14 knockdown significantly reduced the volume of the tumor at week 5 (P < 0.05), which implied that METTL14 knockdown could inhibit tumor formation and growth." (PMID 38326804, 2024). "METTL14 expression is low in BCa tumor-initiating cells (TIC)." (PMID 38632251, 2024). "Early on, a study demonstrated that METTL3 or METTL14 might be a tumor suppressor for GSCs since knockdown of METTL3 or METTL14 expression by shRNA increased GSC growth and self-renewal." (PMID 38398118, 2024). "Furthermore, co-immunoprecipitation studies in tumor cells have demonstrated that the binding affinity of METTL3 for METTL14 is significantly lower than that of METTL14 for METTL3." (PMID 38965238, 2024). "In addition, we assessed the expression of molecules such as ANKRD22, GINS3, POLE2, PLEK2, FERMT1 and METTL14 in subcutaneous tumours and lung metastatic tissues." (PMID 39021049, 2024). "Inhibition of METTL14 not only promotes the proliferation and accumulation of cytotoxic tumor-infiltrating CD8 + T cells, but also induces the secretion of IFNC, CXCL9, and CXCL 10, which enhances the efficacy of immunotherapy and inhibits cancer proliferation." (PMID 39289775, 2024). "Therefore, we first examined the subcellular localization of METTL3 and METTL14 through co-immunofluorescence staining in tumor tissues and EC109 cells." (PMID 38965238, 2024). "Whether METTL3 and METTL14 play a tumorigenic or tumor-suppressor role in cancer remains controversial and inconsistent across various studies." (PMID 39103890, 2024). "METTL14 showed a tumor-suppressive effect in RCC and was downregulated compared to normal controls." (PMID 38503745, 2024). "Moreover, FTO and ALKBH5 function as tumor suppressors by inhibiting METTL3 while promoting METTL14 expression." (PMID 37580808, 2023). "Thus, METTL14 drove epitranscriptomic regulation in the tumor microenvironment, suggesting paths for the development of potential immunotherapies targeting tumor-associated macrophages." (PMID 37152066, 2023). "Through research and analyses, it was found that METTL14 level was negatively linked with tumor size, metastasis stage, pathological grade, and TNM stage, and METTL14 could increase lymph node metastasis, liver metastasis and mortality rate of BC mouse model." (PMID 37701836, 2023). "METTL14 also plays an important role in a variety of tumours." (PMID 36880874, 2023). "However, there are also other studies showing that ectopic expression of METTL14 increased tumor cell survival ability, proliferation and migration ability." (PMID 37701836, 2023). "METTL14 facilitates GGR to suppress UVB-induced skin tumorigenesis." (PMID 37124930, 2023). "Knockout of METTL14 enhanced invasion ability and tumor proliferation ability." (PMID 37701836, 2023).
tumor (continued). "METTL14 affects tumor angiogenesis in a manner that is related t to TRAF1." (PMID 38053093, 2023). "They suggested that METTL14 knockdown could impair the tumour aggressiveness because METTL14 could maintain the methyltransferase complex and m6A abundance." (PMID 37284313, 2023). "Thrombospondin 1 (THBS1), a tumour suppressor, was identified as the target gene of METTL14." (PMID 37284313, 2023). "Another study demonstrates that depletion of METTL3 or METTL14 could increase the sensitivity of anti-PD-1 therapy by supporting the function of cytotoxic tumor‐infiltrating CD8 T cells." (PMID 37965577, 2023). "Notably, the results we have summarized show that METTL14 from tumor cells has a completely opposite effect of METTL3." (PMID 37152066, 2023). "METTL14 is a well-known RNA m6A that plays a vital role in tumor growth by controlling RNA work." (PMID 36873735, 2023). "Finally, tumor formation in nude mice was performed to verify the role of the METTL14/PLAGL2/β-catenin signaling axis." (PMID 36873735, 2023). "Moreover, IHC results shown that METTL14 knockdown resulted in appreciably decreased Caspase7 staining in tumor cells of the xenografts, which indicated that there was less apoptosis in the METTL14 knockdown group." (PMID 36810285, 2023). "Moreover, the downregulation of METTL14 was involved in tumor metastasis, and it performed an adverse prognostic factor for survival without recurrence in HCC patients." (PMID 37469973, 2023). "The reduction of METTL14 contributes to the promotion of tumor metastasis in CRC." (PMID 37915034, 2023). "Moreover, circRNA_103239 inhibited tumour growth in vivo, and the expression of circRNA_103239 was regulated by METTL14-mediated m6A modification." (PMID 38021156, 2023). "METTL14 has a distinct glycolysis-regulating effect in tumours." (PMID 36859310, 2023). "The mRNA expression levels of YTHDC2, YTHDF1, YTHDF3, IGF2BP1, and IGF2BP3 were significantly increased in tumour tissues compared with paired normal breast tissues, while the METTL14, WTAP, FTO, and IGF2BP2 expression levels were significantly decreased in tumour tissues." (PMID 36632454, 2023). "Zhang reported that YTHDF1 can be mediated by METTL14 overexpression, enhancing the stability of Pten mRNA in an m6A-dependent manner and thereby inhibiting the proliferation and migration of tumor cells, activating AKT signaling, and suppressing tumor progression." (PMID 38202722, 2023). "In vitro and in vivo experiments, knocking down METTL14 suppressed tumor metastasis." (PMID 37215454, 2023). "In summary, our findings suggest the tumor-suppressing role of METTL14 in CRC progression." (PMID 37283789, 2023). "Taken together, these results suggested that METTL14 expression was downregulated in CRC and might be associated with tumor progression." (PMID 37283789, 2023). "Moreover, FTO and ALKBH5 negatively regulated METTL3 and positively regulated METTL14 expression levels, enhancing their role as tumor suppressors of CRC." (PMID 37580808, 2023). "As a METTL14 downstream target, Notch1 is vital in tumour oncogenesis and TICs self-renewal." (PMID 37284313, 2023). "In addition, METTL14 significantly inhibited the ccRCC migration and invasion in vitro and in vivo, suggesting that METTL14 has a tumor-suppressor role." (PMID 35036065, 2022). "Additionally, knockdown of TROAP reversed these inhibitory effects of METTL14 on tumor cell proliferation." (PMID 35251990, 2022). "It was further found that the reduction of Ebi3 expression level in C1q + cells can restore the anti-tumor killing ability of CD8+ T cells, while the loss of METTL14 expression can reduce the m6A modification level of Ebi3 mRNA in C1q + cells and promote the increase of its transcription level." (PMID 35614935, 2022).